CRP (C-reactive protein)
Diseases named in the same sentence as CRP in open-access papers (continued):
Sharing a sentence is not in itself a finding about the gene and the disease.
infection (continued). "Lower CRP values typically indicate a higher likelihood of mild or self-limiting infections with a good prognosis and, thus, preclude the need for antibiotics." (PMID 36673130, 2023). "C-reactive protein (CRP) is an acute phase reactant and its serum level can rise nearly 1000 fold in active infection." (PMID 37483708, 2023). "When the CRP decreased by half or <30 mmol/L, the infection was considered to be effectively controlled." (PMID 37768971, 2023). "C-reactive protein is a product of an acute-phase response during infection, responsible for clearing the invading pathogens." (PMID 37111135, 2023). "The degree of inflammation in the body during the beginning of an infection is clinically reflected by the CRP index." (PMID 37777768, 2023). "As the currently used clinical indicators to assess the severity of infection, hs-CRP and PCT show good efficacy in diagnosing disease severity in adults." (PMID 37180431, 2023). "One study found that CRP is more accurate than X-rays in predicting late chronic and early postoperative infections." (PMID 37189111, 2023). "The relationship between CRP and its cutoff level for early detection of active infections has been extensively studied in different populations so far16–19." (PMID 37016028, 2023). "In a similar manner, multiple bacterial-induced host proteins, including procalcitonin, C-reactive protein (CRP), and Interleukin-6, have been previously suggested to support the diagnosis of infection with limited precision." (PMID 37892652, 2023). "As part of the immune system, WBCs usually increase in number when inflammation or infection occurs, and simultaneously, CRP produced by the liver is released into the bloodstream." (PMID 38136423, 2023). "Liver and electrolyte levels were normal, but CRP was elevated in response to tumor progression, IL-2 administration, or infection." (PMID 36765608, 2023). "Among the factors induced by the infection is the C-reactive protein (CRP), an acute-phase protein mainly produced in the liver by hepatocytes." (PMID 37724104, 2023). "Low cellularity in CSF and low levels of C-reactive protein are consistent with a weak inflammatory response to this infection." (PMID 37508953, 2023). "Among the participants, 58% had CRP concentrations >3 mg/L, 12% had concentrations ≥10 mg/L, and there was a clear outlier of 59 mg/L, indicating possible infection or an inflammatory condition in this participant." (PMID 37107316, 2023). "The direct pathways include bacterial invasion and infection, and the indirect pathways include increases in C-Reactive protein (CRP) and interleukin-6 (IL-6)." (PMID 37239434, 2023). "C-reactive protein (CRP) was significantly higher in cases of infection than in relapse (64.7 mg/L vs. 31.5 mg/L, [10.6; 120], p = 0.001)." (PMID 36982631, 2023). "CRP in combination with other markers of inflammation are used as indicators of infection in preterm infants." (PMID 37496672, 2023). "It has also been proposed that CRP can be taken into account as an indicator of infection, alongside a body temperature >38.2 °C." (PMID 37873776, 2023). "On the contrary, PCT increases within 4 h after infection and peaks at 6 h, and CRP increases within 12–24 h and peaks 20–72 h after pathophysiological stress." (PMID 37214473, 2023). "Compared to other markers such as PCT and CRP, it is more specific for bacterial infection due to its direct involvement in the pathomechanism of infection and is a fragment of the CD14 receptor-lipopolysaccharide complex." (PMID 36994432, 2023). "A significant increase in C-reactive protein (CRP) suggests the possibility of infection, and all other results, such as serum creatinine (Scr), total bilirubin (TBIL), and direct bilirubin (DBIL), were unremarkable." (PMID 37559456, 2023). "First, CRP is sensitive to any form of inflammation, meaning that inflammation unrelated to PD, such as an infection, will increase CRP levels." (PMID 37251392, 2023).
infection (continued). "TRAIL, IP-10, and CRP exhibit different responses to infection in children under and over 90 days, prompting the need for further studies focusing on the derivation of a new algorithm intended for this specific population." (PMID 37956117, 2023). "This suggests that CRP is expessed immediately after Gram-positive bacteria infection and plays a critical role in the early stage of such infections." (PMID 37986183, 2023). "But even they cannot reflect the inflammatory activity by themselves because in other situations when an infection or tissue necrosis occurs CRP and ESR increase." (PMID 38137357, 2023). "On univariable analysis of 50 patients undergoing PEG, Delta CRP was the only predictive factor of peristomal infection." (PMID 37189057, 2023). "Patients with CRP values ≥ 10 mg/L more often had infections (36/86, 42%) than patients with values < 10 mg/L (10/61, 16%, p = 0.001)." (PMID 36441359, 2023). "In these 3 patients, the cultures were negative when the spacer was inserted and the compression suture was applied, additionally, the last CRP and leucocyte levels were within normal limits, so that infection eradication is very likely – Table I." (PMID 37969515, 2023). "Among the 102 patients, one had a CRP of 2.26 mg/dl and was considered to have a mild or moderate infection." (PMID 37711763, 2023). "In premature neonates, the reference values for CRP are lower, as is its increase in response to infection." (PMID 36978375, 2023). "CRP is a non‐specific inflammatory protein marker, which rises sharply in plasma when the body is affected by infection or tissue injury and plays an important protective role in the formation of innate immunity in the body." (PMID 37310092, 2023). "Cricopharyngeal muscle opening and nutritional (hemoglobin, albumin and prealbumin) and infection (white blood cells and C-reactive protein) indicators were improved in both experimental and control groups, but statistically superior in the former." (PMID 38082316, 2023). "Three patients exhibited signs of infection in their blood work, manifesting elevated C-reactive protein values (4.6–9.3 mg/dL, normal <0.5 mg/dL)." (PMID 38137098, 2023). "Whenever there is inflammation due to an infection or tissue damage, inflammatory cytokines drive the liver’s epithelial cells to release a lot of CRP." (PMID 37176503, 2023). "It increases and decreases faster in the course of infection than the more routinely used inflammatory marker C-reactive protein (CRP)." (PMID 36978440, 2023). "We found that PSP showed a very good discriminative ability for both investigated study endpoints ICU mortality and infection severity; better in comparison to CRP, similar to PCT." (PMID 37707744, 2023). "ROC curve of baseline CRP and infection in WON had an area under curve (AUROC) of 1, with a sensitivity of 87.5% and specificity of 100% at a cutoff of 49.5 mg/L." (PMID 36895535, 2023). "Misdiagnosis of infection leads to overuse of antibiotics, with fever, elevated C-reactive protein (CRP) levels, and white blood cell (WBC) being the most common features in patients treated with antibiotics." (PMID 37008914, 2023). "C-reactive protein (CRP) can increase rapidly in the case of inflammation, infection, and injury, activate complement and enhance the phagocytosis of phagocytes to eliminate the pathogenic microorganism." (PMID 37849797, 2023). "Mice with endogenous CRP levels that are low even after an inflammatory stimulus were reported to be protected against infections with Bacillus subtilis and Salmonella typhimurium by Achatina CRP (ACRP)." (PMID 37860004, 2023). "Key areas of inflammation and host responses to infection mediated by CRP include the complement pathway, phagocytosis, nitric oxide (NO) release, and cytokine production." (PMID 37107001, 2023).
infection (continued). "The patients had substantial symptoms of AT, clear clinical signs of infection, and highly elevated C-reactive protein (mean: 167 mg/L) and neutrophil count (mean: 11.6 × 109/L) suggestive of bacterial infection." (PMID 37386401, 2023). "The levels of PCT and CRP were (1.97 ± 0.13) μg/L and (7.34 ± 2.66) mg/L, respectively, in the infection group after treatment, which was significantly lower than the levels before treatment." (PMID 37296721, 2023). "The ESR and CRP can also be helpful, as elevations in these values are seen more commonly in other conditions, such as osteomyelitis or infection." (PMID 37788033, 2023). "To conclude, patients with community-acquired bacteremia or high CRP levels should be carefully investigated for focal infection." (PMID 37640802, 2023). "For instance, in patients with an infection, a decrease in CRP is usually interpreted as disease resolution." (PMID 37150798, 2023). "CRP and procalcitonin are of protein structure and are created as the response to inflammation and/or infection." (PMID 36769843, 2023). "General information, operative time, intraoperative bleeding, ESR and CRP at one week postoperatively, time on antibiotics, total drainage, days in hospital, incision infection rate and secondary debridement rate were compared between the two groups." (PMID 37563683, 2023). "Infection was associated with increased absolute number of neutrophils as well as neutrophil percentage, NLR, CRP and PCT levels." (PMID 37761321, 2023). "AUC for CRP was 0.82 (0.78–0.86), P < 0.001, with a cutoff of ≥ 40 mg/L in predicting an infection diagnosis with a sensitivity of 75% and a specificity of 76%; the AUC for NLR was 0.73 (0.69–0.78)." (PMID 37016028, 2023). "Currently, serial measurements of C-reactive protein and leucocytes serve to monitor the development of infection in women with PPROM." (PMID 36098832, 2023). "Concerning CRP, we observed that the frequency of patients with elevated values was higher at T3 and T4 when infection confirmation was at T2, and as for patients with SI confirmation at T3, the difference was found from T2 to T4." (PMID 37755950, 2023). "Nevertheless, general practitioners still use traditional markers such as white blood cell count (WBC), C-reactive protein (CRP) or fibrinogen to identify an apparent infection or the severity of systemic invasion." (PMID 38002294, 2023). "Infection was diagnosed based on symptoms and local clinical signs in addition to laboratory investigations (elevated leucocyte count and C-reactive protein) as well as isolation of microbes in preoperative punctures and/or intraoperative swabs." (PMID 37845299, 2023). "CRP is a major acute phase reactant that rises acutely and rapidly in stress,infection, and tissue damage." (PMID 37403893, 2023). "All patients had features of the pediatric IM syndrome, and elevated levels of markers of active infection (e.g., CRP)." (PMID 37041976, 2023). "CRP is an acute-phase protein synthesized in the liver and is expectedly elevated in inflammatory states such as infection or tissue injury." (PMID 37629728, 2023). "Investigating the association between infection sites and PCT and CRP offers meaningful perspectives on their potential utility as biomarkers for assessing the severity of UTIs." (PMID 37821527, 2023). "For instance, CRP levels in patients with SIRS were higher when complicated by additional infection and peaked around days 2–3 after admission." (PMID 36769613, 2023). "The pre-operative and post-operative haematological indexes were tested to assess the infection control; the post-operative CRP level in the internal fixation group was lower than that in the external fixation group." (PMID 36862164, 2023). "This conclusion is further supported by the evidence that CRP concentrations are significantly influenced not only by infections, but by several other factors also, making the definition of a reliable cut-off value very difficult." (PMID 37627653, 2023).
infection (continued). "CRP, an acute-phase protein, has a half-life of 19 h, and white cell count is a commonly used marker of postoperative inflammation and infection." (PMID 37744382, 2023). "In fact, our results provide compelling evidence of the higher predictive value for infection diagnosis of CRP over PCT, using a longitudinal, time-dependent analysis of these biomarkers." (PMID 37834754, 2023). "In orthopedics, the relationship between preoperative serum CRP levels and the occurrence of infections in planned primary arthroplasty procedures has already been discussed." (PMID 37107100, 2023). "Intensive care was needed in 2.2% of all the 407 infection episodes, in 4.9% of the 103 episodes with a CRP of 200 mg/l or higher and in 1.3% of the 304 episodes with a lower CRP level (P = 0.049)." (PMID 37314998, 2023). "Members of the panel also agreed that CRP testing is preferrable to procalcitonin—another marker that can differentiate severe from self-limiting infections." (PMID 36673130, 2023). "The surgeon usually sets a time for the second procedure once the erythrocyte sedimentation rate and the C-reactive protein rates are back to normal levels; the rates of these proteins are usually elevated, when there is an infection in the body." (PMID 37242643, 2023). "Induction chemotherapy, hemorrhage, and infection at the time of diagnosis, and laboratory data, including blood urea nitrogen, C-reactive protein, and lactate dehydrogenase, were used to predict the D30 prognosis." (PMID 37762881, 2023). "In all infectious episodes, our patients presented with fever above 39 °C and high CRP levels, typically above > 100 mg/dl, already during the first 3 days of the infection." (PMID 36319802, 2023). "The CRP, a sensitive biomarker of infection, inflammation, and tissue damage, is more sensitive than serum cortisol in detecting surgical trauma and can assess various surgical procedures in dogs, peaking 24 h postoperatively." (PMID 37915948, 2023). "WBC and CRP are direct reflections of inflammation and infection, and CRP is also a marker of acute inflammation." (PMID 36945041, 2023). "And CRP can play a crucial role in the immune response against infection by participating in the activation of the complementary system." (PMID 37685276, 2023). "Here we identified that CRP was the best predictor of disease severity among our investigated biomarkers, with suPAR levels being correlated with Delta infection, while LDH, sTREM-1 and HGF proved to best discriminate between survivors and non-survivors." (PMID 37388734, 2023). "Infection-related laboratory markers (white blood cell count, erythrocyte sedimentation rate, and C-reactive protein values) were assessed at 3, 6, and 16 weeks postoperatively." (PMID 37888163, 2023). "In particular, elevated levels of acute phase proteins such as CRP and SAA have been associated with trauma-related pathophysiology as levels of these proteins have been found to increase during infection and trauma." (PMID 37022674, 2023). "The D30 prognosis was based on induction chemotherapy, hemorrhage, and infection at the time of diagnosis and laboratory data, including blood urea nitrogen, C-reactive protein, and lactate dehydrogenase." (PMID 37762881, 2023). "Higher CRP serum levels in patients with unfavorable outcome indicate a fulminant course of the infection." (PMID 35618853, 2023). "A higher post-removal CRP was seen in those meeting our infection definition (infected 20.18 mg/l [5.23, 33.10], uninfected 5.95 mg/l [1.57, 17.12], W = 797, p = 0.005)." (PMID 38250594, 2023). "The rise in the C-reactive protein, as an early indicator of infection or inflammation, also supports the acute state of the disease." (PMID 40729210, 2023). "In the present study we also intended to measure CRP directly at the nursing home when infection was suspected, but due to too few measurements (n = 11), we omitted this result in our analyses." (PMID 37737163, 2023).
infection (continued). "IL-6 is a cytokine expressed at the earliest stage of tissue injury and infection that induces the synthesis of C-reactive protein (CRP) and fibrinogen in the acute phase response." (PMID 38813035, 2023). "The overexpression of C-reactive protein (CRP) is known at the site of inflammation and infection, as it is an acute inflammatory protein." (PMID 38155869, 2023). "Median baseline C-reactive protein (CRP) was higher in infection group 76 (IQR=34.8) mg/L vs asymptomatic group, 9.5 mg/dl (IQR=13.6), p<0.001." (PMID 36895535, 2023). "For patients that have tested positive for COVID, CRP POCT can be useful for disease prognosis, as research has shown that raised CRP >40 mg/L is indicative of severe infections and complicated courses, indicating a need for close follow-up or hospitalization." (PMID 37324137, 2023). "We observed in this study that patients treated with a 90-min protocol, who also shows depressed WBC and unspecific late CRP elevations, had more organ space infections compared to the short protocol with oxaliplatin." (PMID 36631814, 2023). "Meanwhile, AuNPs/MOFs (HKUST-1) complexes containing massive Cu2+ ions served as EC probes to show the expression of C-reactive protein (CRP), an effective indicator of infection, with a low LOD of 0.2 ng mL−1." (PMID 38032432, 2023). "CRP stands as one of the most widely employed inflammation biomarkers, reflecting the intensity of inflammation within the initial 1 to 3 days following infection." (PMID 37986183, 2023). "CRP facilitates the judgment of blood culture results and patient prognosis after the occurrence of infection." (PMID 37510130, 2023). "CRP is recognized as one of the main markers of systemic inflammation and/or severe infection, as a low-cost assay, as easily assessable, and, finally, as largely available." (PMID 37685758, 2023). "Soon after, his infection worsened from 7 December 2020 onward, with a temperature of 38.2°C and CRP of 76.8 mg/L." (PMID 36651731, 2023). "Circulating levels of CRP increase rapidly during the acute-phase response, which can be initiated by infection, inflammation, or trauma." (PMID 37251392, 2023). "The serum CRP level is frequently used as a screening test for infection due to its simplicity, affordability, and sensitivity." (PMID 37731439, 2023). "More recently, it has been proposed that the LE strip test can be used as a reliable tool for diagnosing the persistence of infection and outperforming the serum CRP and ESR assays." (PMID 37187468, 2023). "Regarding the simultaneous removal of circulating biomarkers, alternative tools to assess resolution of infection are needed along with such TPE-driven changes in humoral inflammatory parameters (such as CRP or PCT)." (PMID 37150798, 2023). "This underscores IL-6’s potential as a valuable tool to ascertain the likelihood of CRP elevation and therefore the probability of infection, particularly in patients undergoing regular blood tests." (PMID 38255366, 2023). "The examination of PCT and CRP levels across different infection sites provided intriguing insights." (PMID 37821527, 2023). "Collectively, our results suggested that high ferritin and PCT levels in the early stages of infection and the continuous increase of CRP levels in the later period indicate a poor prognosis in SFTS patients." (PMID 37143532, 2023). "Serum levels of PCT and CRP rapidly increase in response to infection, thus these markers are commonly used to assess the severity of infection, particularly for Gram-negative bacilli." (PMID 38106471, 2023). "While very high CRP levels are generally indicative of active infection or injury, moderately high values tend to reflect systemic inflammation." (PMID 37388285, 2023). "Herein, the role of myricetin (400 and 600 mg/kg) in stimulating the immune status of broiler chickens before infection was clear through boosting IgG and lowering CRP levels." (PMID 37237892, 2023).